IFNG (interferon gamma)
Diseases named in the same sentence as IFNG in open-access papers (continued):
Sharing a sentence is not in itself a finding about the gene and the disease.
infection (continued). "However, as opposed to the antibody response, prior infection did not result in increased numbers of IFNγ producers and that held true for all vaccination groups." (PMID 38501661, 2024). "These PAMs and proteins such as serine protease with the CLIP domain (T1I0A9), interferon gamma, and superoxide dismutase (A0A0P4VG48) are proteins related to the induced immunity of the insect; that is, they are expressed only after the host has been exposed to infection." (PMID 38568999, 2024). "This becomes rate‐limiting during the course of an infection and efficient competition for IL‐2 requires the persistent expression of CD25 which can be enhanced by other cytokines such as type‐I IFNs and IL‐12 or suppressed by cytokines such as IFNγ and promotes additional rounds of cell division." (PMID 38039407, 2024). "When comparing QX-314 and vehicle IAV infected mice, we observed a significant decrease in IL-1β and IFNγ, a reduction in the number of interstitial macrophages and CD8 T cells, plus a small improvement in overall lung histopathology all at day 8 post-infection." (PMID 38626267, 2024). "In particular, a very high background IFNγ was observed in macaque No. 45,912 of the mock-immunized group, this could indicate any ongoing infection or another physiological process." (PMID 39460266, 2024). "We did not observe changes in IFNγ+ macrophages or monocytes in response to infection." (PMID 38295799, 2024). "Moreover, while IFNγ produced by conventional CD4 T memory cells that expand early during infection can dampen CMV persistence, this is not sufficient to fully curtail replication." (PMID 38236791, 2024). "This included the acute efficacy model (interferon-gamma knockout mice, IFN-Gamma KO) which may be more representative of infection in young children, and a chronic efficacy model developed herein which may be more representative of chronically infected immunocompromised adults." (PMID 39441903, 2024). "To characterize the impact of IFNγ and IL-10 blockade on immune responses to SARS-CoV-2 infection, we analyzed transcriptional profiles of BAL cells isolated at baseline and days 3, 7, 14 and 28/35 after infection using Nanostring transcriptomics (n = 752 immune response genes)." (PMID 38950078, 2024). "Indeed, β2-AR signaling is a cell-extrinsic negative regulator of IFNγ production by NK cells at early stages of infection and can have negative effects on virus control." (PMID 39134803, 2024). "Higher numbers of IFNγ-expressing CD4+ T cells and higher frequencies of proliferating (Ki-67+) CD4+ T cells were nonetheless observed after viral antigen stimulation in the SGs of Cd4Cre/+Arg1flox/flox versus Cd4+/+Arg1flox/flox mice during the chronic phase of infection with MCMV." (PMID 37440306, 2023). "Studies have indicated that animals that have been successfully immunized with a subunit or live attenuated B. bovis or are persistently infected and have survived the acute stage of infection may rely on CD4+ T cells that are specific to the antigen and produce interferon gamma (IFN-γ)." (PMID 37563668, 2023). "Hence, the original observation, using conventional SCoV2 RBD ELISA, was further analyzed and confirmed by more stringent SCoV2 RBD ELISA, immunoblot analysis, in vitro FCoV2 infection blocking assay with SCoV2 RBD, and, finally, cellular IFNγ immune responses to SCoV2 RBD." (PMID 37112894, 2023). "Pro-inflammatory (IFNγ, IL-6, TNFα), Treg (IL-10, TGFβ1, TGFβ3), Th9 (IL-9), Th17 (IL-17), and Th2 (IL-4, IL-13) cytokines, total IgM and IgG, as well as gene expressions of FoxP3, STAT5+, IFNγ-R1, and ROR alpha+, were measured at day 1, day 7, day 14, day 21, and day 28 post-infection." (PMID 37569646, 2023). "Furthermore, during infection and cancer, A2AR engagement seems to inhibit via IL-15 signaling blockade, the generation of human CD39+NK cells endowed with a potent degranulation capacity and overexpression of IFNγ and TNFα." (PMID 37753093, 2023).
infection (continued). "To confirm that IAV-specific CD4 and CD8 T cells were Ifnγ+, we stained cells from IAV-infected reporter mice with MHC I and MHC II tetramers containing immunodominant IAV nucleoprotein (NP) peptides, NP368-74, and NP311-325, respectively at days 10 and 40 post-infection." (PMID 37842651, 2023). "In pregnant mice, IFNγ+ and GZB+CD8+Tem subsets were increased by 36.6% and 184% in response to challenge infection, and frequencies of these subsets were further increased by 29% and 127%, respectively, when pregnant mice were vaccinated before challenge infection (p < 0.05–0.001)." (PMID 38104118, 2023). "Thus, prenatal exposure to IFNγ alone increased self‐renewal capacity and output of both Tom+ HSCs and transient GFP+ drHSCs upon primary transplantation, similar to our observations with the Pru infection of intermediate virulence." (PMID 37259639, 2023). "In fact, patients with the acute/juvenile form of the disease are presented with a T helper type 2 (Th2) and Th9 profile, with low production of interferon-gamma (IFNγ), high levels of interleukin (IL)-4, IL-5, IL-10 and IL-9, and they do not control the infection." (PMID 37108883, 2023). "In the case of the individual in the non-infected group with a clear IFNγ response to the peptides, this effect can likely be attributed to a non-detected infection or to cross-reactivity with other coronaviruses, rather than to a priming effect of the COVARNA mRNAs 6 days earlier." (PMID 38250827, 2023). "Knowing that IFNγ plays a prominent role in Ot control and pathogenesis, it will be important to further investigate whether early IFN signaling contributes to the diversity of bacterial clearance in Karp vs. Gilliam infection." (PMID 38091346, 2023). "It is possible that the excessive inflammation resulting from infections by M. tuberculosis HN878 may surpass on one hand the requirement of IFNγ for myelopoiesis, as seen in BCG, and on the other hand, the limiting effect of type I IFN, as seen in M. tuberculosis H37Rv infections." (PMID 37383236, 2023). "However, when assessing the amount of IFNγ produced, there were no detectable differences for either cell type when compared between infection routes." (PMID 35898505, 2022). "Furthermore, IFNγ expression in intraepithelial and splenic NK cells and CD107 expression of splenic NK cells significantly increased at 3 dpi compared to 0 dpi in both groups and then decreased until 21 dpi to levels before infection." (PMID 35120583, 2022). "After infection, naïve CD4 T cells differentiate into type 1 T helper (Th1), Th2, Th17, T follicular helper (Tfh), or regulatory T cells (Treg) lineages, CD4+ Th1 cells are the major effector lineage that mediates chlamydia clearance via interferon-gamma (IFN−γ) secretion." (PMID 36677333, 2022). "Similarly, an increased fraction of degranulating and IFNγ-producing CD8+ T cells upon LCMV GP33 peptide restimulation was seen in ERKSEM mice at Day 7 but not at Day 10 post infection." (PMID 36846018, 2022). "While IFNγ, IL-4, IL-10, and IP-10 did not seem to directly correlate with antibody response amongst our cohorts, they were elevated in moderate and severe COVID-19 disease, compared to mild infection." (PMID 36865568, 2022). "In our study there was an important increase in pro-inflammatory cytokines (IL1β, IL6, TNFα, IL18, IL23) upon infection in all the groups analyzed in comparison with age-related control samples, as also seen for the immunoregulatory cytokines IL10 and IL17A, and for Th1 IFNγ NLF." (PMID 36561744, 2022). "Moreover, increased release of tumor necrosis factor alpha (TNFα), interferon-gamma (INF-γ), and even interleukins produced during infection reduce the synthesis and secretion of lipoproteins, as well as alteration in the distribution of lipoproteins from intravascular to extravascular space." (PMID 35096202, 2022).
infection (continued). "This is in line with recent reports, suggesting that ACE2 and TMPRSS2 expression might be prerequisite for BSG and NRP1 to exert their infection-potentiating activity Interestingly, previous studies have shown that ACE2 expression is regulated by IFNα and IFNγ signalling." (PMID 35837388, 2022). "In summary, vaccination prior to Omicron infection modifies humoral and transcriptional responses with higher antibody and neutralization titers and lower interferon gamma activation than that found in unvaccinated individuals either with or without prior infection." (PMID 35784346, 2022). "Again, in line with our hypothesis of exaggerated responses to lung infection, many of the top upstream regulators identified by IPA were associated with enhanced inflammation (TNF, IFNG, and IL1B) and infection with Gram-negative bacteria (TLR4)." (PMID 36264633, 2022). "However, Interferon gamma (IFNγ) and tumor necrosis factor (TNF) could be detected in respective tests for this subject 6 weeks after infection." (PMID 35577791, 2022). "Here, we demonstrated that Att-S74-T3Bo infection induces alterations in innate immune myeloid and lymphoid cells in peripheral blood, eliciting significant levels of the pro-inflammatory cytokines TNFα, CXCL10, and IFNγ in sera as early as 3 days post-infection." (PMID 36466866, 2022). "Functional polarization was most evident for IFNγ-producing MAIT cells, with TNF-producing MAIT cells displaying a similar but less pronounced pattern and the abundance of GM-CSF-producing MAIT cells increasing throughout the infection in all organs, except for the kidney." (PMID 34272362, 2021). "Unlike the type II IFN, IFNγ, type I IFNs are part of the initial phase of innate immunity and do not require adaptive immune activation to reach therapeutic levels in the body during infection." (PMID 33684179, 2021). "The role of ILC1s in protection is also unclear, as only about 25% of ILC1s produced IFNγ on day 4 after infection, but almost none did on day 30, although the accumulation of these cells in the genital tract continued until at least day 30 after infection." (PMID 34938670, 2021). "Notably, the production of IFNγ required the activation of both STING and MyD88 pathways indicating previous unknown crosstalk between STING and TLRs pathways during infection." (PMID 34512626, 2021). "Moreover, humans regularly exposed to Mtb or cattle exposed to Mb do not always develop signs of infection, i.e., remain negative in IFNg-release assay or skin testing." (PMID 34307535, 2021). "Similarly, infection with the protozaon Trypanosoma cruzi in TKO mice resulted in reduced MHC I expression and altered CD8+ effector T cell function, in both quantity and quality as there were fewer overall CD8+ effector cells and fewer IFNγ producers." (PMID 33968021, 2021). "To test whether IFNG-induced IDO activity had an impact on chlamydial development, we treated HL-60 and HeLa cells with 0–20–40–80 IU/ml IFNG and measured the direct and recoverable chlamydial growth at 48 h post-infection." (PMID 34819931, 2021). "To assess the effect of such transcriptional changes on PUFA biosynthesis, we quantified macrophage’s ability to convert a deuterated derivative of the ω6 precursor LA into downstream products upon infection with Mtb, with or without IFNγ priming, between 6 and 24 hr post infection." (PMID 34951591, 2021). "Finally, we observed increased thymocyte death via apoptosis after infection, independent of both IFNγ and iNOS; and a decrease on active caspase-3 positive thymocytes, which is not observed in the absence of iNOS expression." (PMID 34987496, 2021). "Additionally, there was no expression of IFNγ and iNOS which is due to the constant increase in the fold change of TGFbeta (0–45 min post infection), depicts that TGFβ is a strong anti-inflammatory cytokine which suppresses the expression of IFNγ and iNOS." (PMID 35011356, 2021).
infection (continued). "Multicolor flow cytometry was utilized to analyze the CD4+ and CD8+ T cell populations and their intracellular production of the cytokines IFNγ, TNF, and IL2 (single, double, and triple combinations) associated with both the lethal and nonlethal murine models of infection." (PMID 34287349, 2021). "After infection of a prototypical Th1-inducing pathogen, Toxoplasma gondii, splenic Tbx21 mRNA levels increased 4-fold in wild type mice, but not in Ifnγ−/−mice, indicating that IFN-γ is essential in inducing T-bet expression." (PMID 34675939, 2021). "Indeed, sheep did not resist the experimental infection by virulent strain and cattle did not react positive to IFNG, test of cellular immunity." (PMID 34117312, 2021). "Inspired by our grown awareness of the importance of recognition avidity, we first studied the functional avidities of IDE-specific IFNγ+ CD8+ T cells and verified the absence of IDE-specific responses after infection with mCMV ΔIDE as well as successful back-mutations A9X in mCMV rev-IDE." (PMID 34451420, 2021). "We initially compared the number of IFNγ-producing cells—as measured by ELISpot after stimulation of PBMC in vitro with a SARS-CoV-2 peptide library—between hospital staff members up to three months after vaccination and patients up to twelve months after infection." (PMID 34960185, 2021). "In the mouse, Th1-directed IFNγ is important in stimulating antibacterial activity in macrophages with reactive oxygen species (ROS) more important in the earlier stages and reactive nitrogen species (RNS) pathways activated in the later (chronic) phase of infection." (PMID 34684248, 2021). "Furthermore, substantially higher amounts of IFNγ and IL-4 were produced in the splenocyte supernatants of rAd5-YFV vaccine-immunized mice than those from rAd5-LcrV vaccinated animals in response to an infection." (PMID 33514747, 2021). "This RORyt+ T-bet+ ILC population is an important early source of IFNγ in the lamina propria during STM infection, and it would be interesting to examine whether this may also contribute to the GM-CSF produced in the intestine after STM infection." (PMID 33414524, 2021). "Consistent with a minimal impact of Rb treatment in enhancing NP396–404-specific CD8 T cells following acute LCMV-Arm infection, no alteration in the number of IFNγ-producing NP396–404-specific CD8 T cells was observed in Rb treated LCMV-Arm infected CD4−/− mice." (PMID 34206262, 2021). "The fact that both IFNγ and chemokines need to be spatially and temporally targeted on CCR2+Ly6C+ monocytes at sites of infection to promote their effector responses may represent an evolutionarily conserved mechanism to prevent systemic tissue damages to the host." (PMID 34516896, 2021). "However, a recent study indicated that H. pylori coated with excess cholesterol prior to infection failed to block the IFNγ-mediated inflammatory pathway." (PMID 34506250, 2021). "(A) Activities of PUFA biosynthetic enzymes in resting or IFNγ-primed BMDMs, either left untreated (Ctrl), or infected with Mtb and treated with a FADS2 inhibitor (iFADS2) or vehicle control, as determined by a conversion assay from 6 to 24 hr post infection using the ω6 precursor LA-d11." (PMID 34951591, 2021). "Therefore, it is conceivable that CD4 T cells are attracted by CXCL9/10 sources, being myeloid cells or SGECs in the vicinity of sites of infection, in order to facilitate the encounter of MCMV antigen-presenting cells and consequently to perform their effector functions, such as IFNγ production." (PMID 34959486, 2021). "Although we were not able to measure IFNγ responses in a comparable cohort with mild infection at earlier time points, there was a clearly higher IFNγ response from patients hospitalized with severe infection at 2–4 weeks post-infection." (PMID 34960185, 2021).
infection (continued). "Reports show IFNγ inhibits GM-CSF, and experimental evidence in mice model shows primary DENV infection is IFNγ-dependent and STAT1-independent, which might be the reason for increased IFNγ and low GM-CSF during primary infection." (PMID 34447698, 2021). "However, the analysis of IFNγ, a product of the adaptive immune response (CD4 and CD8 T cells), showed a trend toward reduced expression in immunized IL-6 KO mice after the lethal infection with influenza virus." (PMID 33193346, 2020). "Here we report that IFNγ priming and the induction of GBPs are necessary for caspase-4 activation in human epithelial cells and monocytes/macrophages during infection with the Gram-negative bacterium Salmonella or after cytosolic LPS delivery by transfection or electroporation." (PMID 32581219, 2020). "Although the frequency of IFNγ-producing CD4+ T cells was significantly reduced in IL-6−/− mice 21 days after Mtb infection, comparable amounts of IFNγ-secreting CD4+ T cells could be detected during the following course of infection." (PMID 33375150, 2020). "Notably, before starting emapalumab treatment the child had developed several infections (disseminated BCGitis, adenoviral infection, Stenotrophomonas maltophilia bacteremia, invasive pulmonary aspergillosis) which did not worsen with IFNγ blockade." (PMID 33424859, 2020). "IFNγ could not further improve the recognition of cells in which antigen presentation was already optimal after in vitro infection with ΔvRAP virus." (PMID 32351904, 2020). "When the same experiment was performed with H. hammondi sporozoites, prior infection failed to suppress IFNγ-induced IRF1 activation, suggesting that sequence differences in the IST locus may determine species-specific differences in the host response." (PMID 32574210, 2020). "In Phase 1, during the first 7 to 8 days post infection (DPI), both infectious virus and viral RNA increase rapidly, followed by clearance of infectious virus that occurs primarily through cooperative effects of anti-SINV antibody and the cytokine interferon-gamma (IFN-γ)." (PMID 31963302, 2020). "Importantly, in these cases CCL3 is essential for protective mechanisms involving the recruitment of effector CD8+ T-cells and macrophages to the sites of infection, robust early production of cytokines (TNF and IFNγ), induction of cytolytic activity and generation of radical oxygen intermediates." (PMID 32194558, 2020). "However, manipulation through T. gondii ROP5 does not fully explain how CD8 T cells commit to making IFNγ in response to infection." (PMID 32853276, 2020). "Since CXCL10 secretion is induced by IFNγ treatment in a variety of cell types (CXCL10 is also known as interferon-γ-inducible protein 10 or “IP-10”) and T. gondii IST is known to block IFNγ-induced responses during infection, we performed multiple assays with T. gondii strains lacking TgIST." (PMID 32574210, 2020). "The role played by ROS-producing macrophages at the chronic stage of infection has not been evaluated yet, but it seems likely that at this stage of the disease, most of them are activated by IFNγ to induce the iNOS pathway to produce NO and ONOO with trypanocidal activity." (PMID 33376582, 2020). "At 2 weeks post infection following needle inoculation in the ear, Axl-/-Mertk-/- mice showed significanly decreased IL-10 production from both CD4+ and CD8+ T cells which was accompanied by increased frequencies of IFNγ and iNOS expression from CD4+ T and myeloid cells, respectively." (PMID 33137149, 2020). "Protection against active TB is known to require a clearly delineated T-helper type 1 (Th1) response, mediated by interferon-gamma (IFNγ), interleukin-2 (IL2), and tumor necrosis factor-alpha (TNFα), which may clear infection or drive it into an immune-mediated containment or latency." (PMID 32498074, 2020).